CRMA (cardiomyocyte maturation associated lncRNA)
Synonyms: FLJ30313; CARMA; formerly C20orf200; NCRNA00335; C20orf166-AS1; MIR1-1HG-AS1
Gene: Long non-coding RNA gene on chromosome 20 (62,540,159 to 62,551,535, reverse strand). Ensembl gene ENSG00000174403.
Diseases named in the same sentence as CRMA in open-access papers:
CRMA is named in the same sentence as 13 diseases in open-access papers, as found by Europe PMC text mining. Sharing a sentence is not in itself a finding about the gene and the disease. The quoted sentences say what the papers report.
Fulminant hepatitis (1 paper, 2020). Acute hepatitis complicated by acute liver failure with hepatic encephalopathy occurring less than 8 weeks after the onset of jaundice. "Pre-treatment with an adenovirus delivering the coding sequence for CrmA potently inhibited anti-Fas antibody-induced fulminant hepatitis in male BALB/c mice." (PMID 32244484, 2020).
lymphoma (1 paper, 2010). A malignant (clonal) proliferation of B- lymphocytes or T- lymphocytes which involves the lymph nodes, bone marrow and/or extranodal sites. "These investigators used a genetically tractable in vivo myc driven lymphoma model in which death receptor signaling was compromised due to overexpression of CrmA, a viral caspase-8 inhibitor, or due to deficiency of TRAIL." (PMID 20145726, 2010).
myocardial infarction (1 paper, 2024). Gross necrosis of the myocardium, as a result of interruption of the blood supply to the area, as in coronary thrombosis. "Targeting both extrinsic and intrinsic apoptosis pathways has demonstrated improved systolic function in myocardial infarction conditions by applying cowpox virus protein, crmA, at reperfusion." (PMID 38399343, 2024).
pancreatic cancer (1 paper, 2012). "Fifth, overexpression studies in pancreatic cancer cells indicated that both caspase-8 (CrmA) and NF-κB-dependent mitochondrial proteins (Bcl-2, and Mcl-1) were involved in the process of TRAIL sensitization." (PMID 22829912, 2012).
prostate carcinoma (1 paper, 2012). A carcinoma that arises from epithelial cells of the prostate gland. "To further investigate the mechanisms of TRAIL sensitization by GSK-3 inhibition, we employed PPC-1 prostate cancer cell overexpressing Bcl-2, Bcl-XL, and Mcl-1 to inhibit the mitochondrial pathway, or cytokine response modifier A (CrmA) to inhibit the death receptor pathway of caspase activation." (PMID 22829912, 2012).
infection (3 papers, 2021 to 2023). The state of being infected such as from the introduction of a foreign agent such as serum, vaccine, antigenic substance or organism. "It was hypothesised that the infection pattern is associated with vigorous bacterial adhesion and replication and subsequent lesion development, which correlates with the expression of the proteins GapA and CrmA." (PMID 36056451, 2022). "Certain MG cytoadherence proteins (GapA, CrmA, PlpA, and Hlp3) play a crucial role in the pathogen’s respiratory tract colonization and infection." (PMID 38322423, 2023). "This variant lacks the GapA and CrmA proteins, which is why in vivo trials with RCL2 resulted in lower infection rates than with Rlow, but significantly higher than with Rhigh." (PMID 36056451, 2022). "The most crucial step for initial infection is the adhesion of M. gallisepticum to the host cell surface which is achieved by cytoadherence proteins GapA and cytoadherence-related molecule A (CrmA)." (PMID 34765664, 2021). "Previous reports suggest that the absence of GapA and CrmA in mutant strains of M. gallisepticum does not cause infection, proving the importance of these two cytoadherence proteins in infection." (PMID 34765664, 2021). "The important M. gallisepticum membrane-bound proteins, GapA and CrmA, are key factors for host cell interaction and the bacterial life-cycle, including its gliding motility, although their precise role in the individual infection step is not yet fully understood." (PMID 36056451, 2022).
tumor (2 papers, 2021 to 2022). "Regarding FasL, indirect evidence using tumour cells expressing inhibitors of the death receptor pathway like CrmA (a cowpox protein) or FLIP, suggested that FasL was also involved in NK cell-mediated tumour immunosurveillance." (PMID 35651603, 2022).
cancer (1 paper, 2009). A tumor composed of atypical neoplastic, often pleomorphic cells that invade other tissues. "We transduced cancer cells to overexpress crmA which inhibits initiator caspases including caspase-1 and caspase-8 in the death-receptor pathway, or Bcl-2, a well-known inhibitor of multiple caspases in the mitochondrial pathway." (PMID 19247489, 2009).
CRMA also shares sentences with these, for which no sentence is quoted: breast carcinoma (1 paper); diabetes (1); mycoplasma infection (1); psoriasis (1); skin disorder (1).